TFEB (transcription factor EB)
Diseases named in the same sentence as TFEB in open-access papers (continued):
Sharing a sentence is not in itself a finding about the gene and the disease.
congestive heart failure (2 papers, 2019 to 2021). Failure of the heart to pump a sufficient amount of blood to meet the needs of the body tissues, resulting in tissue congestion and edema. "Increases in myocardial autophagic flux occur earlier than increases in TFEB activities, while both occur in the compensatory stage of cardiac proteinopathy; both autophagic flux and the TFEB activities become impaired in the congestive heart failure stage." (PMID 31297061, 2019). "Once congestive heart failure develops, both autophagy and TFEB signaling become impaired." (PMID 31297061, 2019). "At 6 months of age when congestive heart failure is apparent in R120G mice, both LC3-II flux and TFEB activities were severely suppressed, while mTORC1 activity increased." (PMID 31297061, 2019).
cyst (2 papers, 2023 to 2024). A sac-like closed membranous structure that may be empty or contain fluid or amorphous material. "TFEB was primarily localized in the nucleus of the cyst lining cells from kidneys of KspCre+; Tsc2fl/fl mice." (PMID 38195686, 2024). "TFEB was primarily localized in the nucleus of the cyst lining cells from kidneys of Tsc2 KO (KspCre+; Tsc2fl/fl) mice and was relocalized outside of the nucleus upon this short-term Rapamycin treatment, consistent with our in vitro data." (PMID 38195686, 2024). "Rapamycin should promote TFEB translocation to the nucleus secondary to mTORC1 inhibition and thus stimulate cyst growth." (PMID 36794754, 2023). "This study reports that nuclear TFEB translocation characterizes cyst-lining epithelia in several models of polycystic disease, a pathway normally associated with nutrient deprivation and stress." (PMID 36794754, 2023). "Consistent with this nuclear localization of TFEB in KspCre+; Tsc2fl/fl mice, lysosomal number was increased in cyst lining cells relative to normal adjacent tubular cells or to renal tubular cells of control mice, as assessed by transmission electron microscopy (TEM)." (PMID 38195686, 2024). "Fourth, nuclear TFEB was observed in cyst-lining epithelia of human PKD tissue." (PMID 36794754, 2023). "Finally, if nuclear TFEB characterizes cystic epithelia, then could specific TFEB-mediated gene products be used as biomarkers for cyst burden in patients with PKD?" (PMID 36794754, 2023).
enterovirus infection (2 papers, 2020 to 2023). "We dissect phosphorylation events in the mTORC1 signalling pathway and we discover a role for transcription factor EB (TFEB), which was previously not known to be associated with enterovirus infection, in the non-lytic release of enterovirus particles via extracellular vesicles (EV)." (PMID 32859902, 2020).
HIV-1 infection (2 papers, 2021 to 2025). The type species of lentivirus and the etiologic agent of acquired immunodeficiency syndrome (AIDS). "In macrophages, the interaction of toll-like receptor 8 (TLR8) and HIV-1 induces autophagy by Beclin 1-dependent dephosphorylation of transcription factor EB (TFEB) and subsequently its nuclear translocation during the initial stages of HIV-1 infection." (PMID 33669846, 2021). "Further studies are warranted to investigate TFEB localization and phosphorylation status, as well as the expression and activity of IRGM and GABARAP proteins, in the context of vitamin D3 supplementation during HIV-1 infection." (PMID 40514685, 2025).
infarction (2 papers, 2023 to 2024). A localised pathological necrosis of tissue resulting from obstruction of the blood supply usually by a thrombus, an embolus, or vascular torsion. "TFEB overexpression was demonstrated to alleviate cardiac remodeling following infarction." (PMID 39872885, 2024).
injury (2 papers, 2021 to 2025). Damage inflicted on the body as the direct or indirect result of an external force, with or without disruption of structural continuity. "mTORC1/TFEB signaling has been identified to play a role in autophagy in cardiomyocytes after myocardial ischemia-reperfusion injury." (PMID 39884255, 2025).
insulinoma (2 papers, 2021 to 2023). "In particular, pancreatic insulinomas (n = 24) showed a higher expression of the autophagic genes BECN1 (p < 0.001), MAP1LC3B (p < 0.001), SQSTM1 (p = 0.008), TFEB (p < 0.001), PRKAA1 (p = 0.038), and PRKAA2 (p = 0.019) compared to NF-pNET (n = 7)." (PMID 36835048, 2023).
intervertebral disc degeneration (2 papers, 2022 to 2023). "TFEB, as the main controller of autophagy and lysosome biogenesis, has been linked to senescence in both in vivo and in vitro models of intervertebral disc degeneration, where TFEB decreases its nuclear abundance, leads to lysosomal dysfunction, and decreases autophagy flux." (PMID 36231114, 2022).
ischemia (2 papers, 2021 to 2024). A hypoperfusion of the BLOOD through an organ or tissue caused by a PATHOLOGIC CONSTRICTION or obstruction of its BLOOD VESSELS, or an absence of BLOOD CIRCULATION. "TFEB is also activated in neurons during the first phase of ischemia, where it elicits an adaptive activation of autophagy." (PMID 38590779, 2024). "The decreased activity of TFEB in the later phases of ischemia was not dependent by mTORC1 activation, which is a TFEB inhibitor." (PMID 38590779, 2024).
kidney stone (2 papers, 2021 to 2022). "In 2020, the idea of the protectiveness of autophagy associated with kidney stone was first proposed and focused on targeting transcription factor EB." (PMID 36213233, 2022). "In addition, we have presented the first evidence that RSV exerts its anti-oxidative stress activity and preventive effects against kidney stone formation, at least in part, through the activation of TFEB-induced autophagy (Graphical Abstract)." (PMID 33718378, 2021).
leukemia (2 papers, 2023 to 2025). A malignant (clonal) hematologic disorder, involving hematopoietic stem cells and characterized by the presence of primitive or atypical myeloid or lymphoid cells in the bone marrow and the blood. "These innovative compounds, which also activate differentiation through TFEB, are highly synergistic with arsenic trioxide, and possess interesting pharmacological properties that render them promising drug candidates for leukemia and other tumor types." (PMID 36980800, 2023).
lung adenocarcinoma (2 papers, 2018 to 2025). A carcinoma that arises from the lung and is characterized by the presence of malignant glandular epithelial cells. "We also wanted to determine whether TFEB expression status in lung adenocarcinoma could be associated as a prognostic indicator of disease outcome." (PMID 30013069, 2018). "In the TCGA lung adenocarcinoma data set only 4% of cases show amplification of TFEB (data not shown)." (PMID 30013069, 2018).
lung squamous cell carcinoma (2 papers, 2021 to 2024). "However, the findings depicting TFEB as a negative prognostic factor were obtained on squamous cell lung carcinoma, while in our analysis of TCGA and retrospective cohort, only adenocarcinomas were considered." (PMID 39107857, 2024).
lymph node metastasis (2 papers, 2022 to 2023). "Instead, only a decreased expression of SQSTM1 (p = 0.006), TFEB (p = 0.011), and PRKAA1 (p = 0.001) could be observed in patients with lymph-node metastases (n = 17)." (PMID 36835048, 2023).
Lysosomal disease (2 papers, 2019 to 2020). "Recently, a transcription factor EB (TFEB), which is responsible for the transcription coordination of most lysosomal genes, has been identified, this transcription controller provides a new tool to manipulate and study lysosomal diseases." (PMID 31771289, 2019).
memory impairment (2 papers, 2020 to 2023). "Our findings suggest that TNEA attenuates AD-associated memory impairment via promoting TFEB/TFE3-mediated autophagic clearance of Aβ and NLRP3 inflammasome, and partially reveal the molecular basis of combined acupoints therapy originated from ancient wisdom." (PMID 36732771, 2023). "Therefore, in this study we systematically evaluated the protective effects of C1 in AD animal models and demonstrate that curcumin analog C1 can activate TFEB, promote autophagy and lysosomal activity, attenuate Aβ and Tau pathology, and prevent memory impairment in AD." (PMID 31858697, 2020).
myocardial ischemia (2 papers, 2023 to 2025). A disorder of cardiac function caused by insufficient blood flow to the muscle tissue of the heart. "Similarly, in myocardial ischemia/reperfusion mouse model, METTL3 motivates RNA-binding protein HNRNPD to combine with TFEB pre-mRNA and subsequently restrains the expression of TFEB, while ALKBH5 plays an opposite role." (PMID 36793898, 2023).
non-alcoholic steatohepatitis (2 papers, 2022 to 2024). "We also reported that polydatin could ameliorate non-alcoholic steatohepatitis by restoring the lysosomal acidification in hepatocytes by upregulating TFEB." (PMID 34997207, 2022).
ovarian tumor (2 papers, 2022). "This indicates that the ability of TFEB to upregulate ATP7B expression in response to cisplatin might contribute to the chemoresistance of different ovarian tumor cell lines." (PMID 35053335, 2022). "In xenografted ovarian tumors, ARHI1 expression induces autophagy by inhibiting the PI3K/AKT/mTOR pathway and supporting nuclear localization of the transcription factor EB (TFEB) and Forkhead box O3 (FOXO3a), which in turn mediate the expression of crucial autophagy effectors." (PMID 35158815, 2022).
preeclampsia (2 papers, 2024). Preeclampsia is a hypertensive disorder of pregnancy that is characterized by new-onset hypertension with proteinuria presenting after 20 weeks of gestation, and depending on mild or severe forms may initially present with severe headache, visual disturbances, and hyperreflexia. "Abnormal elevation of ceramide can increase transcription factor EB (TFEB) expression and nuclear translocation, induce lysosomal formation and exocytosis, and lead to excessive autophagy and programmed necrosis of trophoblasts, resulting in the onset of preeclampsia." (PMID 38879866, 2024).
renal angiomyolipoma (2 papers, 2021 to 2022). "TFEB is also primarily nuclear in TSC-associated RCC and renal angiomyolipomas, and in Tsc1/2-null MEFs." (PMID 34253722, 2021).
sarcoma (2 papers, 2019 to 2021). A usually aggressive malignant neoplasm of the soft tissue or bone. "Interestingly, I.J. Davis group reported that TFEB can rescue MITF knockdown in cell sarcomas." (PMID 30634982, 2019).
type 2 diabetes (2 papers, 2021 to 2023). "Most studies have demonstrated lower autophagy activity in cardiomyocytes of type 1 and type 2 diabetes due to activated mammalian target of rapamycin(mTOR) and inhibited AMPK and transcription factor EB(TFEB) signalling in diabetic hearts." (PMID 36562207, 2023).
Ureteral obstruction (2 papers, 2022 to 2024). Obstruction of the flow of urine through the ureter. "Based on the tight association between autophagy and fibrogenesis, the causal role of TFEB in ureteral obstruction-induced kidney fibrosis and fine-tuned mechanisms by which TFEB regulates fibrosis should be deciphered." (PMID 38481802, 2024). "Here, we found that TFEB protein was decreased in both human and mouse of unilateral ureteral obstruction (UUO)-induced fibrotic kidney, and that overexpression of TFEB in mouse kidneys attenuated fibrogenesis." (PMID 38481802, 2024).
Acidosis (1 paper, 2025). Abnormal acid accumulation or depletion of base. "Our findings suggest that TFEB activation through melatonin may be a promising therapeutic strategy for treating acidosis by enhancing autophagy and may provide new therapeutic targets for neurological diseases associated with acidosis." (PMID 39940940, 2025).
acute liver failure (1 paper, 2023). Rapid deterioration of liver function causing encephalopathy and coagulopathy. "A study indicated that the level of autophagy was improved and liver damage was attenuated in chronic and acute liver failure, because of the increased TFEB nuclear translocation." (PMID 37755761, 2023).
acute lung injury (1 paper, 2020). A condition of lung damage that is characterized by bilateral pulmonary infiltrates (pulmonary edema) rich in neutrophils, and in the absence of clinical heart failure. "The study focused on the protection of HRS on lipopolysaccharide (LPS)-induced acute lung injury (ALI) in rat models and the relationship with autophagic regulation and mTOR/TFEB signaling pathway." (PMID 32071922, 2020).
acute promyelocytic leukemia (1 paper, 2023). An aggressive form of acute myeloid leukemia (AML), characterized by arrest of leukocyte differentiation at the promyelocyte stage, due to a specific chromosomal translocation t(15;17) in myeloid cells. "Among them, we focused on arsenic trioxide (ATO), a widely used chemotherapeutic agent for treating acute promyelocytic leukemia (APL), since it activates TFEB, increases lysosomal activity and the accumulation of acidic vesicles, and inhibits OXPHOS." (PMID 36980800, 2023).
adrenal pheochromocytoma (1 paper, 2024). "In order to investigate whether CC also activates TFEB in neuronal cells, firstly, rat adrenal pheochromocytoma cell line PC12 cells stably expressing a TFEB-GFP fusion protein were generated." (PMID 39454957, 2024).
alcoholic hepatitis (1 paper, 2022). Acute hepatitis resulting from ingestion of alcohol. "In patients with alcoholic hepatitis, the authors also observed a decrease in nuclear contents of TFEB in the liver, indicating that TFEB activity may contribute to the pathogenesis of ALD in both humans and murine models." (PMID 35625599, 2022).
alcoholic pancreatitis (1 paper, 2020). Acute or chronic inflammation of the pancreas due to excessive alcohol drinking. "Taken together, our data suggest that TFEB-mediated lysosomal biogenesis plays a critical role in the pathogenesis of alcoholic pancreatitis." (PMID 31987928, 2020). "More importantly, decreased nuclear TFEB and lysosome numbers were also observed in human alcoholic pancreatitis samples." (PMID 31987928, 2020). "In line with our findings in mice, decreased LAMP1 and TFEB nuclear staining were also observed in human alcoholic pancreatitis tissues." (PMID 31987928, 2020). "Thus, our results also imply that the impaired-TFEB-mediated lysosomal biogenesis not only contributes to the experimental alcoholic pancreatitis but also to human alcoholic pancreatitis." (PMID 31987928, 2020). "We investigated the role of transcription factor EB (TFEB), a master regulator of lysosomal biogenesis, in the pathogenesis of alcoholic pancreatitis." (PMID 31987928, 2020).
amyloid cardiomyopathy (1 paper, 2014). "We further demonstrate that restoration of autophagic flux pharmacologically with rapamycin or genetically through overexpression of TFEB protects against AL-LC cardiotoxicity and may represent a novel therapeutic approach for treatment of amyloid cardiomyopathy." (PMID 25319546, 2014).
Anxiety (1 paper, 2024). Intense feelings of nervousness, tension, or panic often arise in response to interpersonal stresses. "TFEB knockout did not affect general locomotion or anxiety‐related behavior." (PMID 39264289, 2024).
asthma (1 paper, 2024). "Immunohistochemistry results showed that the lungs of mice in the asthma group had a large number of inflammatory cells infiltrated and TFEB was highly expressed (P < 0.0001)." (PMID 38664707, 2024). "The results revealed a significantly elevated TFEB mRNA level in the lung tissue of mice within the asthma group compared to the control group (P < 0.01)." (PMID 38664707, 2024). "The Western blot analysis revealed a significant increase in TFEB protein expression in the lung tissue of mice in the asthma group compared to the control group (P < 0.01)." (PMID 38664707, 2024). "TFEB mRNA expression levels were assessed in the peripheral blood mononuclear cells (PBMCs) of both healthy children and those diagnosed with asthma." (PMID 38664707, 2024). "The results revealed a significantly elevated expression of TFEB mRNA in the PBMCs of children with asthma compared to healthy controls, demonstrating statistical significance (P < 0.0001)." (PMID 38664707, 2024). "Additionally, immunofluorescence of sections showed significantly higher TFEB expression on DCs in the asthma group compared to the control group (P < 0.001)." (PMID 38664707, 2024). "Notably, TFEB expression showed a significant increase in the PBMCs of children diagnosed with asthma compared to healthy counterparts." (PMID 38664707, 2024). "Therefore, in this study, we employed RNA-seq to identify differentially expressed genes, while concurrently evaluating the expression of TFEB mRNA in peripheral blood mononuclear cells (PBMCs) from both healthy children and children diagnosed with asthma." (PMID 38664707, 2024). "TFEB might have a vital role in asthma’s development by impacting the antigen presentation of DCs, regulating T cell subgroup differentiation, and influencing cytokine secretion." (PMID 38664707, 2024). "However, it is currently unclear how TFEB changes in asthma and what impact it has on the antigen-presenting function of DCs and T-cell differentiation." (PMID 38664707, 2024). "Our study results first suggested that TFEB has differential expression in asthma DCs, and may be involved in antigen presentation and the immune response process." (PMID 38664707, 2024). "Moreover, by constructing a mouse model of HDM-induced asthma and a co-culture system of bone marrow dendritic cells (BMDCs) and T cells, we comprehensively analyze the role of TFEB in the process of antigen presentation by DCs and in mediating the immune response of CD4 + T cells." (PMID 38664707, 2024). "In an asthma mouse model induced by HDM, the TFEB expression in lung tissue DCs was evaluated." (PMID 38664707, 2024).
Ataxia (1 paper, 2023). Ataxia refers to impaired coordination of voluntary muscle movement. "Trehalose is a well-known activator of TFEB, which has improved mitochondria morphology in human fibroblasts with an ataxia-associated mutation in the C-terminal HSP70-interacting protein (CHIP)." (PMID 38033125, 2023).
autosomal dominant polycystic kidney disease (1 paper, 2023). Autosomal dominant form of polycystic kidney disease. "Nuclear TFEB also characterized cystic epithelia but not noncystic tubular epithelia in human patients with autosomal dominant polycystic kidney disease." (PMID 36794754, 2023).
blastoma (1 paper, 2016). A malignant neoplasm composed of undifferentiated cells. "Conversely, GDC-0941, an inhibitor of phosphatidylinositol-3-kinase, upregulates TFEB, leading to death of glio-blastoma cells." (PMID 27992857, 2016).
brain injury (1 paper, 2025). Acute and chronic (see also brain INJURIES, CHRONIC) injuries to the brain, including the cerebral hemispheres, CEREBELLUM, and brain STEM. "Here, we sought to discern the possibility of serum TFEB as a prognostic biomarker of moderate–severe traumatic brain injury (msTBI)." (PMID 40324256, 2025).
cervical carcinoma (1 paper, 2017). A carcinoma arising from either the exocervical squamous epithelium or the endocervical glandular epithelium. "We transiently overexpressed TFEB (TFEB-3xflag) for 48 h in human cervical carcinoma (HeLa) cells, revealing an increase in protein expression compared with control cells transfected with pcDNA3." (PMID 28084445, 2017).
chondrosarcoma (1 paper, 2023). A malignant cartilaginous matrix-producing mesenchymal neoplasm arising from the bone and soft tissue. "The suppression of TFEB-mediated autophagy increased apoptosis induced by salidroside in chondrosarcoma." (PMID 37305393, 2023).
collecting duct carcinoma (1 paper, 2026). "In conclusion, this study retrospectively analyzed the clinicopathological and prognostic data of 105 metastatic nccRCC patients at our centre, including 41 pRCC, 31 TFE3/TFEB-rearranged RCC, 26 unclassified RCC, 3 chRCC, 3 FH-RCC and 1 collecting duct carcinoma." (PMID 41578672, 2026).